IL6 (interleukin 6)
Diseases named in the same sentence as IL6 in open-access papers (continued):
Sharing a sentence is not in itself a finding about the gene and the disease.
myeloma (continued). "In particular, IL-6 has been implicated in the pathogenesis of osteolysis associated with Paget's disease, Gorham-Stout syndrome, and multiple myeloma." (PMID 22235336, 2012). "Genes dowmregulated in multiple myeloma cells exposed to the pro-proliferative cytokine IL-6 versus those with N-ras-activating mutations." (PMID 20500821, 2010). "A number of growth and anti-apoptotic factors, including interleukin-6 (IL-6), have been implicated in sustaining the malignant myeloma cells." (PMID 19187270, 2009). "The main stimulator of CRP synthesis in the liver is interleukin 6 (IL-6), which is associated with diseases of old age such as multiple myelomas, chronic lymphatic leukaemia and renal cancer, and is higher in older than in younger subjects." (PMID 18706087, 2008). "For example, IL6, a well-known stimulus for myeloma cells, has been reported to be elevated and associated with clonal expansion in Gaucher patients." (PMID 17655728, 2007). "The best characterized of these proteins is interleukin-6 (IL-6), a cytokine previously linked to a number of malignancies including renal, myeloma and prostate." (PMID 19675761, 2007). "In addition to other resistance mechanisms, using GAB1 and SHP2-GAB1 binding mutants, GAB1 has been shown to be associated with the IL-6-induced dexamethasone resistance mechanism in multiple myeloma cells." (PMID 37627207, 2023). "For example, severe RA symptoms are tightly correlated with elevated IL-6 levels in the synovial fluid, while IL-6 overproduction has been associated with poorer outcomes of multiple myeloma as it may promote the growth of myelomas and plasmacytomas." (PMID 36077865, 2022). "Raised IL-6 levels can be caused by both myeloma precursor cells and the presence of MCs." (PMID 34631562, 2021). "Furthermore, IL-6 overproduction is thoroughly linked to neoplastic diseases such as sarcoma in Kaposi, myeloma multiple, renal carcinoma, and prostate cancer." (PMID 34833950, 2021). "In mice, IL-6 deficient BM and T cell grafts significantly reduced myeloma relapse post-ASCT." (PMID 33777050, 2021). "The NRF2 level in OBs could interfere with interleukin (IL)-6 expression, which is associated with bone metabolism and myeloma cells." (PMID 32937821, 2020). "Following the initial observation that EZH2 is over expressed in aggressive myelomas, we demonstrated that EZH2 expression is driven by IL-6 and is required for the proliferation of growth-factor-independent human myeloma cell lines (HMCLs) harboring a ras mutation." (PMID 29774113, 2018). "Additionally, myeloma cell-derived IL-1β, also encoded by an NF-κB-target gene, promotes IL-6 production by inducing canonical NF-κB signaling in BMSCs." (PMID 29772694, 2018). "Moreover, POEMS is characterized by the presence of monoclonal Ig, usually IgG or IgA with lambda light chain, and KSHV encodes for viral IL6 that is functionally active on human myeloma cells." (PMID 25607954, 2015). "This may be due to the risk of IL-6 exposure increasing the likelihood of myelomas as IL-6 is responsible for the differentiation and proliferation of immune cells." (PMID 25309775, 2014). "Likewise, circulating DCs isolated from multiple myeloma patients exhibit an impaired capacity for T cell stimulation that is partly caused by IL-6-mediated inhibition of DC development." (PMID 21799877, 2011). "It should be noted that 23 (28,75%) of multiple myeloma patients (of which only 2 in the early stages of disease) had IL–6 pos.–174 GG genotype and this genotype was associated with increased serum levels of IL–6." (PMID 22567049, 2011). "Finally, a high IL-6 serum level is often associated to worse progression-free survival and overall survival in Non Hodgkin Lymphoma, myeloma, renal carcinoma and breast adenocarcinoma." (PMID 19956602, 2009).
myeloma (continued). "An alternative hypothesis posits that the etiology may involve a breakdown in immune regulation, marked by increased expression of the interleukin (IL)-6 gene—a cytokine with wide-ranging impacts on the immune system and hematopoiesis, closely associated with the development of multiple myeloma." (PMID 39104429, 2024). "Furthermore, knockdown of MnSOD reduced the IL-6-caused myeloma cell resistance to radiation." (PMID 33198328, 2020). "For example, targeting IL6 (e.g., Johnson and Johnson’s drug sirukumab), or the IL6 receptor (e.g., Regeneron’s sarilumab) could be tailored perhaps by using BMAT biomarkers, knowing now that BMAds, especially myeloma-associated adipocyte lineage cells, are a source of IL6." (PMID 33680918, 2020). "In addition, we found that IL-6 expression is strongly down-regulated in miR210 deficient myeloma cell line; this suggests that miR210 might be essential to hypoxic-induced IL-6 expression." (PMID 30108468, 2018). "Moreover, myeloma cell-derived Jagged may activate Notch receptors in BMSCs via heterotypic interaction and promote IL-6 secretion, ultimately causing IL-6 levels to increase in the BM microenvironment." (PMID 30154786, 2018). "Interestingly, IL6-deficient mice are resistant to induction of multiple myeloma." (PMID 25132836, 2014). "Further, IL-6 has been implicated in age-associated diseases (such as lymphoproliferative disorders, multiple myeloma, osteoporosis, and Alzheimer's disease) and frailty; and, it is postulated that certain clinically important late-life changes are due to an inappropriate presence of IL-6." (PMID 18652680, 2008). "Pairwise protein analysis confirmed cosecretion of IL-1β and IL-6 in macrophages stimulated with IL-4/IL-13, which were identified as part of a critical pathway in multiple myeloma before." (PMID 42292686, 2026). "Albumin, a component of both the CONUT score and ISS, can be influenced by inflammatory cytokines like IL-6 from the myeloma microenvironment and changes in body fluid volume." (PMID 40003698, 2025). "In support, the pro-tumor activity of the inflammasome can be proven by the blockade of IL-1β using Anakinra, which proved to prolong the PFS of myeloma patients through the reduction of IL-6 levels, crucial for tumor cell proliferation and survival." (PMID 39857785, 2025). "In multiple myeloma, therapeutic strategies should focus on reversing the tumor-supportive phenotype of mesenchymal stem cells, potentially via targeted inhibition of IL-6 or CXCL12 signaling." (PMID 40140850, 2025). "IL-6 exerts a suppressive effect on NK cells and stimulates tumor cell proliferation, survival, and metastasis in myeloma." (PMID 40136679, 2025). "BBR has previously demonstrated modulations to miR-21 of U266 and RPMI-8266 cells, another IgG-producing myeloma cell line, potentially through IL-6/STAT3, and the consequential increase in programmed cell death 4 gene expression." (PMID 41294852, 2025). "In multiple myeloma, mesenchymal stem cells facilitate immune evasion through the secretion of cytokines, including IL-6 and CCL2, which enhance the survival and proliferation of multiple myeloma cells while suppressing immune cell activity." (PMID 40140850, 2025). "Pucci and colleagues have found that myeloma-derived extracellular vesicles upregulate the expression of programmed death ligand 1 (PD-L1) and IL-6 in naive macrophages." (PMID 40136679, 2025). "In particular, it has been shown that mouse monoclonal anti-N isotype IgG1 antibodies in the presence of N protein are able to stimulate IL-6 production by myeloma-derived K-ML2 cells and in macrophage cultures." (PMID 40558099, 2025). "Based on these results, we propose that visfatin utilizes the NF-κB signaling pathway to stimulate the production of IL-6 in multiple myeloma (MM) cells." (PMID 40392374, 2025). "IL-6 is particularly important in enhancing myeloma cell proliferation and survival, as well as supporting drug resistance." (PMID 40002248, 2025).
myeloma (continued). "In accordance with the clinical diagnosis of multiple myeloma (MM), IL-6 and IL-8 levels were found to be significantly elevated in MM patients." (PMID 40392374, 2025). "Multiple myeloma secretes IL-6, VEGF, and BAFF, promoting tumor growth, angiogenesis, and immune suppression, with high levels associated with advanced disease and reduced survival." (PMID 40801653, 2025). "RDW correlates with elevated acute inflammatory markers like ESR, CRP, and interleukin-6, and is a biomarker in conditions like kidney disease and multiple myelomas." (PMID 41466195, 2025). "DC dysfunction stems from various molecular mechanisms involving direct interactions between myeloma cells and DCs or high levels of cytokines, especially IL-6, in the TME." (PMID 40313957, 2025). "Current risk stratification models for MGUS/Smoldering Multiple Myeloma (SMM) increasingly incorporate inflammatory and metabolic biomarkers, with our findings supporting CXCL10 and IL‐6 as potential candidates for dynamic monitoring." (PMID 41498034, 2025). "Arsenic acid has been shown to inhibit STAT3 activation in myeloma cells 39, consequently reducing IL-6 release." (PMID 40386065, 2025). "In MM, osteoclast activity is abnormally increased due to cytokines (e.g., interleukin (IL)-6, IL-1, and IL-17) produced by interactions between myeloma cells and the bone marrow." (PMID 40978969, 2025). "In multiple myeloma (MM), MSCs from patients show altered osteogenic differentiation potential, increased secretion of pro-inflammatory cytokines such as IL-6 and CCL2, and enhanced support for tumor growth." (PMID 40140850, 2025). "Multiple myeloma further exploits the marrow niche by stimulating osteoclast-mediated bone resorption and leveraging IL-6 to enhance drug resistance." (PMID 41346447, 2025). "U266 is one of the most used myeloma cell lines, which expresses IL-6, a crucial component for the maintenance and proliferation of myeloma cells." (PMID 40649999, 2025). "Myeloma cells produce IL-6 both autocrinely and paracrially, and this cytokine offers protection to MM cells." (PMID 40392374, 2025). "Between in 1988 and 1989, three laboratories independently reported the promoting effect of IL-6 on the proliferation of in human multiple myeloma (MM)." (PMID 38520006, 2024). "Human bone marrow–derived mesenchymal stromal cells (hMSC) stimulate myeloma cell expansion (e.g., IL6) and simultaneously retain myeloma cells via chemokines (e.g., CXCL12) and adhesion factors." (PMID 38598843, 2024). "IL-6 is also a crucial growth factor in myeloma cells, which is indispensable in MM tumorigenesis, maintenance of malignant cell clones, and monoclonal immunoglobulin production." (PMID 38564026, 2024). "Existing research suggests that the deletion of RB1 disrupts the downregulation of IL-6 by its gene product, pRB, leading to elevated IL-6 levels and the subsequent malignant proliferation of myeloma cells." (PMID 39664374, 2024). "It secretes IL-6, another pro-inflammatory cytokine that stimulates survival in myeloma cells, and it stimulates osteoclasts for bone resorption." (PMID 39087203, 2024). "TNF-alpha can stimulate IL-6 secretion by osteoblasts and stromal cells and accumulated IL-6 stimulates the growth of multiple myeloma cells." (PMID 39329904, 2024). "PTK787 not only augments dexamethasone’s myeloma cell growth inhibition but also circumvents IL-6’s protective effect against dexamethasone-induced cell death." (PMID 38900304, 2024). "Interleukin-6 functions as a growth factor for multiple myeloma cells, playing a significant role in their resistance to apoptosis and promoting the formation and activity of osteoclasts." (PMID 39329904, 2024). "In myeloma cells, curcumin has also been shown to inhibit a signal transducer and activator of transcription 3 phosphorylation, thereby suppressing interleukin-6 (IL-6) production." (PMID 39770989, 2024).
myeloma (continued). "It was reported that IL-6 promoted myeloma proliferation, prevented cells from apoptosis, enhanced bone destruction, most importantly, triggered immunosuppression." (PMID 38464531, 2024). "IL-6 is a critical factor in myeloma cell proliferation and survival, playing a pivotal role in the pathogenesis of MM." (PMID 39664374, 2024). "IL-6, a growth and survival factor for myeloma cells, is among those cytokines that activate JAK2 and ultimately augment its downstream signaling effects; and, therefore, JAK inhibitors represent potential therapies for treating MM patients." (PMID 38319731, 2024). "Co-culture of endothelial HUVEC and myeloma cells stimulated formation of new tubes from endothelial cells, when the cultured medium was supplemented with IL-6 or was depleted of HLA-G." (PMID 38877399, 2024). "It has been shown that IL-6 (Interleukin-6), as a critical cytokine, can influence the pathogenesis of myeloma through direct activation of PI3K/AKT and MAPK pathways." (PMID 38460944, 2024). "For example, the VLA4 (Myeloma)–VCAM1 (MSC)-interface activates NFκB in both myeloma and MSCs, inducing IL6 expression in MSCs." (PMID 38598843, 2024). "The IL6 dependency of INA-6 enhanced the resemblance of myeloma cell lines to patient samples, with INA-6 ranking 13th among 66 cell lines." (PMID 38598843, 2024). "In myeloma, IL-6 can activate Erk5 independently of Ras and tyrosine–protein kinase Src(Src), thereby enhancing myeloma cell proliferation." (PMID 38785963, 2024). "The ubiquitinated HIF-1α and HLA-G proteins were identified in the three myeloma cell lines after 4-h treatment with IL-6." (PMID 38877399, 2024). "RUX was able to reduce STAT3 activation and increase apoptosis of myeloma cells in both IL-6 independent and IL-6 dependent lines." (PMID 38319731, 2024). "In the context of CAR T-cell therapy for multiple myeloma, recent research has elucidated the prognostic significance of inflammatory markers, particularly C-reactive protein, ferritin, and interleukin-6." (PMID 39286245, 2024). "Specifically, in the case of myelomas, considering the information mentioned previously, the increased expression of the IL-6 receptor in response to heightened IL-6 release is suggested as a promising target for diagnoses and therapeutic interventions." (PMID 38337668, 2024). "The use of IL-6 monoclonal antibody has shown promising results in treating renal cell carcinoma, prostate cancer, lymphoma, multiple myeloma, and other diseases." (PMID 38828409, 2024). "It has also been shown that TNF-α promotes the growth of myeloma cells and contributes to myeloma bone disease, both directly and through the activation of interleukin 6 (IL-6)." (PMID 39830670, 2024). "For example, in multiple myeloma (MM) cells, IL-6, IGF-1, SDF-1α, tumor necrosis factor-α (TNF-α), and VEGF can promote tumor cell proliferation through the MEK/p42/p44/MAPK signaling cascade." (PMID 38672455, 2024). "An example of how cytokines can induce epigenetic changes and favour the transformation of one phenotype to another is interleukin-6 (IL-6) in multiple myeloma (MM), a neoplasm characterised by abnormal plasma cell development." (PMID 37808081, 2023). "Autocrine and/or paracrine IL-6 secretion induces IL-10 production, further suppressing T cell function, hence promoting myeloma clonal expansion." (PMID 37744361, 2023). "Parthenolide inhibits cell migration and tubule formation by decreasing NF-B, VEGF and IL-6 expression and increasing IB kinase expression in multiple myeloma cells." (PMID 37047552, 2023). "S100A9 induced MDSC to express and secrete inflammatory and pro-multiple myeloma cytokines, including TNFα, IL6, and IL10." (PMID 36923707, 2023). "NF-kB activity in myeloma cells is important for maintaining the interaction with BM stromal cells, because this factor regulates the expression of IL-6, VEGF, and IGF-1, which provides the survival, development, and chemoresistance of myeloma cells around BM." (PMID 36678608, 2023).
myeloma (continued). "It is well known that Interleukin-6 (IL-6) is the main growth factor of human myeloma cells, which acts through its receptor IL-6R." (PMID 37823051, 2023). "TNF-α is a pleiotropic cytokine that mediates inflammatory responses and induces myeloma cells to produce high IL-6 levels." (PMID 37250588, 2023). "Stromal cell derived factor (SDF)-1 upregulates IL-6 secretion in myeloma, which ensures tumor growth, survival, and migration." (PMID 37120508, 2023). "A disadvantage of IL-6 as a systemic marker of myeloma is its ubiquitous nature with respect to inflammation generally and is not specific to myeloma." (PMID 37120508, 2023). "IL-6 also protects myeloma cells against dexamethasone-induced apoptosis by activating protein tyrosine phosphatase." (PMID 37120508, 2023). "The two main sources of autocrine and paracrine secretion of interleukin-6 are malignant myeloma cells themselves and bone marrow niche stromal cells, respectively." (PMID 36928900, 2023). "BOR can suppress phosphorylation of STAT3 induced by IL-6 via myeloma cells and bone marrow stromal cell binding." (PMID 38004369, 2023). "IL-6 activates osteoclasts and promotes defective bone physiology thus provide a measure of the extent of bone disease in myeloma patients." (PMID 37120508, 2023). "SFM-DR can be best described by IL-6 affinity, because IL-6 secretion leads to Bortezomib resistance in myeloma cells." (PMID 36678608, 2023). "Its use in multiple myeloma was attributed to the immunomodulatory and anti-angiogenic activity which downregulates the expression of TNF-α and IL-6 by the stromal cells in the bone marrow, thereby inhibiting the proliferation of multiple myeloma cells." (PMID 36966238, 2023). "HCK-mediated phosphorylation of GAB1 induces proliferation and survival in IL-6-induced multiple myeloma cells." (PMID 37627207, 2023). "Among these cytokines, interleukin 6 plays a key role in the survival and proliferation of malignant myeloma cells." (PMID 36928900, 2023). "A number of studies have indicated that targeting the IL-6 pathway inhibits myeloma growth through inhibition of the nuclear factor kappa B and/or Janus kinase signalling pathways." (PMID 37120508, 2023). "The major cytokines secreted by MMPCs and involved in myeloma cell proliferation, survival, drug resistance, migration, angiogenesis, and osteolysis are IL-6, TNF-α, VEGF, and IGF-1." (PMID 38002311, 2023). "On the other hand, numerous investigations have studied IL-6-triggered dexamethasone resistance in multiple myeloma." (PMID 37627207, 2023). "This response results in increased cytokine production, including interleukin-6 (IL-6), which is a potent myeloma cell growth factor reflecting disease severity and cell proliferation." (PMID 37512137, 2023). "Together with IL-6, IL-2, IL-1β and soluble IL-6 receptor (S-IL-6R) have also been shown to affect the survival of myeloma patients." (PMID 37120508, 2023). "Adipokines, such as leptin and IL-6, induce myeloma cell survival and proliferation, but targeting adipokines in MM or cancer generally has not had great translational success and new targets, based on a better understanding of the pathology, are needed." (PMID 36909335, 2023). "Cytokines tumor necrosis factor (TNF)-α and interleukin (IL)-6, for example, are provided by the niche and can induce proliferation of myeloma cells, creating a tumor-supportive microenvironment." (PMID 37081258, 2023). "INA-6 is one of a few IL-6-dependent MM cell lines and is also quite similar to primary myeloma cells when examined by transcriptomic correlation analysis." (PMID 35005550, 2022). "Osteoclasts have been found to influence myeloma progression via direct crosstalk or release of distinct cytokines including IL-6, IL-3, macrophage inflammatory protein 1 alpha (MIP1α) or expression of receptor activator of NF-κB ligand (RANKL)." (PMID 35847862, 2022).